TTC19 (tetratricopeptide repeat domain 19)
Description:
Required for the preservation of the structural and functional integrity of mitochondrial respiratory complex III by allowing the physiological turnover of the Rieske protein UQCRFS1. Involved in the clearance of UQCRFS1 N-terminal fragments, which are produced upon incorporation of UQCRFS1 into the complex III and whose presence is detrimental for its catalytic activity.
Synonyms: FLJ20343; MGC19520; 2010204O13Rik; MC3DN2
Tractability: PROTAC: ubiquitination databases record sites on it; its protein half-life has been measured.
Gene: Protein-coding gene on chromosome 17 (15,999,783 to 16,045,015, forward strand). Ensembl gene ENSG00000011295.
Subcellular location: Mitochondrion inner membrane
Subcellular location (Human Protein Atlas): Mitochondria
Pathways (Reactome):
Metabolism: Complex III assembly
Gene Ontology:
Molecular function: protein binding
Biological process: mitochondrial respiratory chain complex III assembly; mitotic cytokinesis
Cellular component: mitochondrial inner membrane; mitochondrion; centrosome; midbody
Genetic constraint (gnomAD): Loss-of-function variants: 33 observed, 42.07 expected, observed/expected ratio (o/e) 0.78, 90% interval 0.59 to 1.05. The upper end of that interval is the gene's LOEUF score, 1.05, which puts it in group 4 of 6, group 1 being the genes least tolerant of losing a copy. Missense variants: 463 observed, 435.55 expected, observed/expected ratio (o/e) 1.06, 90% interval 0.98 to 1.15. Synonymous variants: 202 observed, 164.01 expected, observed/expected ratio (o/e) 1.23, 90% interval 1.1 to 1.38.
Gene-disease validity (ClinGen):
ClinGen rates the evidence that TTC19 causes each of these diseases.
Leigh syndrome (autosomal recessive): Definitive. A progressive neurological disease defined by specific neuropathological features associating brainstem and basal ganglia lesions.
mitochondrial disease (autosomal recessive): Definitive.
Homologues: Orthologues: chimpanzee TTC19 (98% identical), macaque TTC19 (97% identical), guinea pig TTC19 (88% identical), mouse Ttc19 (82% identical), pig TTC19 (75% identical), rat Ttc19 (75% identical), dog TTC19 (71% identical), rabbit TTC19 (66% identical), tropical clawed frog ttc19 (44% identical), zebrafish ttc19 (41% identical), Drosophila melanogaster Ttc19 (23% identical), Caenorhabditis elegans ddl-3 (22% identical).
Diseases named in the same sentence as TTC19 in open-access papers:
TTC19 is named in the same sentence as 27 diseases in open-access papers, as found by Europe PMC text mining. Sharing a sentence is not in itself a finding about the gene and the disease. The quoted sentences say what the papers report.
Ataxia (5 papers, 2014 to 2022). Ataxia refers to impaired coordination of voluntary muscle movement. "Recently, mutations in TTC19 have been described in young adults with spinocerebellar ataxia, a 42-year-old man with rapidly progressive neurological disease, and patients with developmental delay in childhood and slowly progressive neurodegenerative disease." (PMID 25887401, 2015). "Clinical symptoms of MC3DN are varied, but in reports on mutations of TTC19, many cases exhibit neurological disorders in adulthood, and some cases present both hemiplegia and cerebellar ataxia." (PMID 24397319, 2014). "TTC19 mutations have been reported in a few patients with heterogeneous phenotypes ranging from early onset neurodegenerative disorders to adult forms with psychiatric manifestations and cerebellar ataxia." (PMID 30030362, 2018). "Mutations in TTC19 have been associated with heterogeneous clinical presentations, including early or late-onset ataxia, cognitive impairment, slowly progressive developmental delay/regression due to necrotizing encephalomyopathy (Leigh syndrome; Atwal, 2013) and psychiatric symptoms." (PMID 25452764, 2014). "Mutations in TTC19 have been rarely associated with mitochondrial disease to date, being described in about ten patients with heterogeneous clinical presentations, ranging from early onset encephalomyopathy to adult forms with cerebellar ataxia." (PMID 25452764, 2014). "Furthermore, patients with homozygous mutations in another assembly factor TTC19 (tetratricopeptide repeat domain 19), such as p.L219*, p.E173*, are found to develop a series of neurodegenerative disorders, including severe psychiatric symptoms, cerebellar ataxia, cognitive impairment, LS and so on." (PMID 36157077, 2022). "In TTC19-mutant cases, ataxia and impairment of cortical functions leading to language or cognitive regression are the clinical hallmarks of infantile-onset forms, whereas psychiatric symptoms are typical of juvenile-adult forms." (PMID 30030362, 2018).
Leigh syndrome (3 papers, 2014 to 2024). "Similarly, TTC19 is a mitochondrial protein crucial for the catalytic activity of complex III, and pathogenic variants of TTC19 are associated with mitochondrial diseases in humans, including Leigh syndrome." (PMID 37505079, 2023). "PARL is described to affect the assembly of complex III through its substrate TTC19 and to regulate coenzyme Q synthesis through COQ4, causing respiratory chain deficits leading to Leigh syndrome-like neuronal degeneration." (PMID 38182793, 2024).
asthma (2 papers, 2020 to 2025). "There were seven eSNPs with cis- or trans-regulatory roles in TTC19 to be associated with severe asthma." (PMID 33066754, 2020). "With the use of a series of bioinformatics analyses, we highlighted 11 important genes such as GNGT2, TLR6, and TTC19 as authentic risk genes associated with moderate-to-severe/severe asthma." (PMID 33066754, 2020). "In summary, current study provides several lines of evidence to support that 11 highlighted genes including GNGT2, TLR6, and TTC19 could be treated as genuine moderate-to-severe/severe asthma-associated genes." (PMID 33066754, 2020). "Interestingly, 4 genes of MPI, DECR2, LNPEP, and TTC19 are newly reported to be involved in severe asthma risk." (PMID 33066754, 2020). "For example, the cis-regulatory eSNP of rs3785631 is associated with severe asthma (PGWAS = 6.37 × 10− 3) and gene expression of TTC19 (PeQTL = 1.79 × 10− 17)." (PMID 33066754, 2020). "There were 8 of 11 genes (8/11 = 72.7%) showing significantly different expression profiles between severe asthma and controls; for example, GNGT2, TLR6, TTC19, LNPEP, SLC22A5 and HLA-DQA1." (PMID 33066754, 2020). "Meanwhile, in an independent dataset of GSE123750, we found that TTC19 (P = 0.0078), TLR6 (P = 0.0086), and GNG12 (P = 0.045) were significantly expressed in severe asthma by comparison with mild-moderate asthma." (PMID 33066754, 2020).
Parkinson disease (2 papers, 2023). A progressive degenerative disorder of the central nervous system characterized by loss of dopamine producing neurons in the substantia nigra and the presence of Lewy bodies in the substantia nigra and locus coeruleus. "We successfully identified four hub genes associated with Parkinson’s disease (PD), namely dld, dlk1, iars, and ttc19, through a combination of differential expression analysis, WGCNA, and machine learning algorithms (LASSO and mSVM-RFE)." (PMID 38051734, 2023).
breast carcinoma (1 paper, 2011). "The downregulation of FYVE-CENT, BECN 1, KIF13A and TTC19 in advanced breast cancer is consistent with the possibility that these proteins may participate in tumor suppression." (PMID 21455500, 2011). "Interestingly, we also observed that the average expression of KIF13A and TTC19 was significantly lower in high vs. low grade breast cancers." (PMID 21455500, 2011).
Cerebellar atrophy (1 paper, 2014). Cerebellar atrophy is defined as a cerebellum with initially normal structures, in a posterior fossa with normal size, which displays enlarged fissures (interfolial spaces) in comparison to the foliae secondary to loss of tissue. "According to the previous reports, all patients harbored homozygous nonsense mutations in TTC19, and head MRI showed characteristic findings including cerebellar atrophy and abnormal intensity at the bilateral inferior olives." (PMID 24397319, 2014).
deficiencies (1 paper, 2014). "Neurodegeneration caused by mutations of TTC19 are classified as mitochondrial complex III deficiencies (MC3DNs), including MC3DN1 [MIM:124000], which is associated with compound heterozygous or homozygous mutations of the BCS1L gene." (PMID 24397319, 2014).
lactic acidosis (1 paper, 2015). Metabolic acidosis characterized by the accumulation of lactate in the body. "For the first time, we describe homozygous missense mutations in TTC19 patients, as well as one patient presenting with episodes of severe lactic acidosis, and one patient with normal MRC complex III activity." (PMID 25887401, 2015). "Neonatal lactic acidosis is found in several types of mitochondrial disorders, but has not been associated with TTC19 deficiency so far." (PMID 25887401, 2015). "Due to the MR imaging and lack of lactic acidosis, western blotting of TTC19 protein was performed revealing only traces of TTC19 protein." (PMID 25887401, 2015).
melanoma (1 paper, 2024). A malignant, usually aggressive tumor composed of atypical, neoplastic melanocytes. "Our analysis identified the PD causative protein TTC19 as interacting with CHMP48, which was regulated by variants that are associated with melanoma." (PMID 38263313, 2024).
mitochondrial complex deficiency (1 paper, 2025). "Mutations in genes such as TTC19, SURF1, and PET100, which are associated with mitochondrial complex deficiency, as well as mutations in MT-ND3 linked to mitochondrial DNA-associated Leigh syndrome and NARP, were identified." (PMID 40336053, 2025).
Progressive encephalopathy (1 paper, 2024). "Patients with loss of function mutations in TTC19 develop progressive encephalopathy associated with a deficiency in complex III." (PMID 38240717, 2024).
tumor (3 papers, 2011 to 2023). "Higher protein expression of TTC19 was closely associated with larger tumor size, more lymph node metastasis, higher histological grade, and poor overall survival in patients with TNBC." (PMID 37928256, 2023). "In addition, we also show that other complex III components are upregulated in the late stages of human high grade serous ovarian cancers (HGSOCs), in which TRAP1 is downmodulated, and identify the assembly factor TTC19 as a novel biomarker of potential clinical interest in this tumor type." (PMID 36510251, 2022).
movement disorder (2 papers, 2017 to 2024). Neurological conditions resulting in abnormal voluntary or involuntary movement, which may impact the speed, fluency, quality and ease of movement. "Here, we report a 13‐year‐old Chinese boy with basal ganglia involvement, manifested with progressive movement disorders, limb weakness, suspicious ataxia, and peripheral neuropathy, with a novel frameshift mutation in the TTC19 gene." (PMID 37927170, 2024). "Patients with TTC19 mutations are described as having an already delayed development which progresses via extrapyramidal movement disorder to a minimal residual state." (PMID 28804536, 2017).
neurodegenerative disease (2 papers, 2014 to 2015). A disorder of the central nervous system characterized by gradual and progressive loss of neural tissue and neurologic function. "TTC19 deficiency is a progressive neurodegenerative disease associated with isolated mitochondrial respiratory chain (MRC) complex III deficiency and loss-of-function mutations in the TT19 gene in the few patients reported so far." (PMID 25887401, 2015). "TTC19 has been reported to be a causative gene of a neurodegenerative disease in Italian and Portuguese families and to be involved in the pathogenesis of mitochondrial respiratory chain complex III (cIII) deficiency." (PMID 24397319, 2014). "In recent years, it has been reported that cases of neurodegenerative disease associated with atrophy of the cerebellar vermis and the cerebral cortex are caused by homozygous nonsense mutations of TTC19 [GenBank:NM_017775] in Italian and Portuguese families." (PMID 24397319, 2014).
infection (1 paper, 2019). The state of being infected such as from the introduction of a foreign agent such as serum, vaccine, antigenic substance or organism. "Conversely, the top 12 downregulated genes, including fermitin family member 1 (FERMT1), signal peptide peptidase like 3 (SPPL3), and tetratricopeptide repeat domain 19 (TTC19), negatively correlated with VA1 infection." (PMID 31671153, 2019).
TTC19 also shares sentences with these, for which no sentence is quoted: cerebellar ataxia (3 papers); cancer (2); Cognitive impairment (2); developmental delay (2); mitochondrial disease (2); colon tumor (1); encephalomyopathy (1); Encephalopathy (1); metastatic tumors (1); mitochondrial complex III deficiency (1); neurological disorders (1); peripheral neuropathy (1).